NEUROD1 (neuronal differentiation 1)
Diseases named in the same sentence as NEUROD1 in open-access papers (continued):
Sharing a sentence is not in itself a finding about the gene and the disease.
prostate carcinoma (7 papers, 2014 to 2026). A carcinoma that arises from epithelial cells of the prostate gland. "NeuroD1 was previously shown to be expressed in aggressive prostate cancer cell lines and prostate cancer samples, although co-expression with chromogranin A was found only rarely." (PMID 24884804, 2014).
breast carcinoma (6 papers, 2011 to 2024). "NEUROD1 DNA methylation has been observed in diffuse large B-cell lymphoma and breast cancer where it was associated with a ten-fold more likely response to neoadjuvant therapy in estrogen receptor-negative cancers." (PMID 21731750, 2011). "Breast cancer patients with positive serum pretreatment NEUROD1 methylation exhibited poor prognosis." (PMID 36313290, 2022). "Analysis of possible targets for miR-29b-1-5p reveals that the top 4 targets, USP28, NEUROD1, LIN9 and WDR26 have all been previously associated with breast cancer." (PMID 30323900, 2018).
glioblastoma (6 papers, 2017 to 2025). The most malignant astrocytic tumor (WHO grade IV). "Here, we used lentiviral vector to overexpress NEUROD1 in U251 glioblastoma biosensor cells using dsRed as a reporter." (PMID 41371337, 2025). "Another point worth noting is that nELAVLs are also upregulated in other glial cell types including microglial and glioblastoma cell lines during NeuroD1-mediated reprogramming." (PMID 37681934, 2023).
glioma (6 papers, 2011 to 2026). A benign or malignant brain and spinal cord tumor that arises from glial cells (astrocytes, oligodendrocytes, ependymal cells). "Here, we report a gene therapy strategy to treat glioma utilizing NeuroD1, a neurogenic transcription factor with demonstrated capacity to reprogram both glial cells and GBM cells into neuronal lineages." (PMID 42088619, 2026). "Our study shows that the Tc immunophenotype in gliomas is characterized by NeuroD1 expression." (PMID 32064038, 2020). "In IDH-mutant gliomas, IDH mutations promote histone methylation marks including H3K27me3 by epigenetic reprogramming Meanwhile, in SHH-MB, EZH2-mediated H3K27me3 marks accumulate at NEUROD1 regulatory elements, suppressing NEUROD1 expression and maintaining tumor cells in an undifferentiated state." (PMID 40599851, 2025).
Obesity (6 papers, 2010 to 2024). Accumulation of substantial excess body fat. "Twelve weeks postpartum, in these subjects with NEUROD1 variants and obesity, we performed an oral glucose tolerance test; both showed a significant reduction in insulin release at 1 and 2 hours when compared with T2D and control subjects." (PMID 28095440, 2017). "Notably, we showed that circGlis3/miR-124-3p/NeuroD1 and Creb1 are involved in pathological changes in β-cells in response to obesity." (PMID 36681689, 2023).
viral infection (6 papers, 2011 to 2022). "We found that FGF2 and EGF stimulation allowed NR-astrocytes exposed to a single NeuroD1 virus infection to be converted into neurons." (PMID 36289433, 2022). "Unexpectedly, NeuroD1 expression in converted neurons showed a significant decrease after 6 months of viral infection, indicating a downregulation of NeuroD1 after neuronal maturation in adult NHPs." (PMID 33224952, 2020). "This is true in monkey brains at 2- and 4-month time points after viral infection, but we observed a significant decrease in NeuroD1 signal within many NeuroD1-mCherry infected cells at 6-month time point." (PMID 33224952, 2020). "In contrast, injection of NeuroD1 plus Dlx2 viruses into the striatum of Cre77.6 transgenic mice revealed a transitional conversion process at different time points following viral infection." (PMID 32107381, 2020). "In the present study, we found that a relatively higher expression level of NeuroD1 induced by repeated virus infections could achieve neuronal reprogramming efficiently from NR-astrocytes." (PMID 36289433, 2022). "However, in NeuroD1-infected areas, MAP2 was partially recovered at 2 months and significantly recovered at 6 months post viral infection (NeuroD1-mCherry columns)." (PMID 33224952, 2020). "We first confirmed the co-expression of NeuroD1 and Dlx2 with immunostaining after viral infection." (PMID 33425896, 2020). "In addition, unlike in the absence of these growth factors, we found that even a single NeuroD1-virus infection together with FGF2 and EGF could effectively induce AtN conversion by 7 dpt." (PMID 36289433, 2022). "Importantly, at both 2- and 6-month time points following viral infection, the NeuroD1-converted neurons showed immunoactivity for Tbr1 signal, suggesting that NeuroD1-based gene therapy can regenerate cortical neurons in the monkey cortex after ischemic injury." (PMID 33224952, 2020). "At 3 days of post-viral infection (dpi), both the control AAV mCherry and the NeuroD1-mCherry-infected cells were astrocytes (top two rows)." (PMID 33250718, 2020). "In contrast, in NeuroD1-treated areas, GFAP-labeled astrocytes were always detected in the vicinity of NeuroD1-converted neurons at 2 months, 6 months, or 1 year after viral infection, and less reactive in morphology compared to the control group (NeuroD1-mCherry columns, green signal)." (PMID 33224952, 2020). "Moreover, multiple NeuroD1-expressing viral infections (3 times) enabled neuronal reprogramming from non-reactive (NR-) astrocytes that were previously shown to be resistant to conversion into neurons with a single infection." (PMID 36289433, 2022). "At both 2- and 6-month time points following viral infection, the SV2 immunostaining showed a significant increase of puncta number in the NeuroD1-infected areas compared to the control mCherry-infected areas, consistent with better neuronal recovery after NeuroD1-treatment." (PMID 33224952, 2020).
adenoma (5 papers, 2013 to 2023). A neoplasm arising from the epithelium. "The E proteins E12, E47, and HEB are known to be expressed in SI crypts and adenomas, and E12 and E47 bind to NEUROD1 to induce transcription of secretin in the duodenum." (PMID 35503250, 2022). "When comparing the average numbers of NeuroD1 expressing cells in all adenoma types by immunohistochemistry, statistically significant differences were seen between corticotropinomas and gonadotropinomas (p=0.02)." (PMID 30719226, 2019). "The average numbers of NeuroD1 expressing cells in normal adenohypophysis specimens were significantly lower than in the adenomas overall (p=0.006)." (PMID 30719226, 2019). "Thus, the NeuroD1 TF was expressed, on average, in 95.5% of cells in all of the investigated adenoma types." (PMID 30719226, 2019). "When the average numbers of NeuroD1 expressing cells were compared in all of the sample groups, including normal adenohypophysis fragments near adenoma boundaries, significant differences were seen between gonadotropinomas and normal adenohypophysis (boundary) fragments (p=0.02)." (PMID 30719226, 2019). "It is worth mentioning that, unlike adenomas, the average number of NeuroD1 expressing cells in normal anterior pituitary was extremely variable (from 14 to 90.22%)." (PMID 30719226, 2019). "Significant differences between the average number of NeuroD1 expressing cells in normal adenohypophysis fragments near adenoma boundaries and in normal pituitary gland were not seen (p=0.8)." (PMID 30719226, 2019).
Huntington disease (5 papers, 2020 to 2022). Huntington disease (HD) is a rare neurodegenerative disorder of the central nervous system characterized by unwanted choreatic movements, behavioral and psychiatric disturbances and dementia. "Impaired neurogenesis and decreased expression of NEUROD1/Neurod1 have also been demonstrated in the hippocampus of the Huntington’s disease R6/2 mouse model and in differentiated neural cultures derived from Huntington’s disease patients." (PMID 34177462, 2021). "In Huntington’s disease model mice, combinatorial expression of NeuroD1 and Dlx2 in striatal astrocytes induces conversion into GABAergic neurons." (PMID 34068607, 2021). "More recently, by combining NeuroD1 and Dlx2 together, we have demonstrated that astrocytes in the striatum of R6/2 mouse model for Huntington's disease can be converted into GABAergic neurons." (PMID 33425896, 2020). "In a separate study on Huntington's disease, we have discovered that combining NeuroD1 and Dlx2 together can successfully convert striatal astrocytes into GABAergic neurons." (PMID 33425896, 2020). "By combining NeuroD1 and Dlx2 together, we further demonstrated that astrocytes in the striatum of mouse model with Huntington’s disease can be directly converted in medium spinal neurons, which not only improved motor functions but also extended the life span of HD mice." (PMID 33224952, 2020).
lung carcinoma (5 papers, 2011 to 2024). "Promoters of ASCL1-and NEUROD1-dependent genes were found as specific targets of lurbinectedin in SCNE lung cancer cells." (PMID 37467967, 2023). "The transcriptome of NE-lung cancers driven by ASCL1 or NEUROD1 has been well studied." (PMID 31324758, 2019). "Recent studies have discovered molecular subtypes of SCNE lung cancer defined by ASCL1 (achaete-scute family bHLH transcription factor 1), NEUROD1 (neurogenic differentiation 1), POU2F3 (POU class 2 homeobox 3), and YAP1 (Yes1 associated transcriptional regulator) transcription factors." (PMID 37467967, 2023). "Furthermore, overexpression of NEUROD1 in non-endocrine lung cancer cell lines activates a neuroendocrine program, underscoring NEUROD1’s role in inducing a neuroendocrine phenotype." (PMID 39105169, 2024). "Thus, ASCL1 and NEUROD1 expression has been used to divide NE-lung cancers into ASCL1High, NEUROD1High, or double-negative subtypes." (PMID 31324758, 2019).
neuroendocrine tumors (5 papers, 2018 to 2022). "Should instead read: In genetically engineered mouse models (GEMMs), it has been shown that murine c-Myc-driven SCLC expresses high level of NEUROD1, which is a key transcriptional factor for the survival and proliferation of neuroendocrine tumor cells." (PMID 30477547, 2018). "In genetically engineered mouse models (GEMMs), it has been shown that murine N-Myc-driven SCLC expresses high level of NEUROD1, which is a key transcriptional factor for the survival and proliferation of neuroendocrine tumor cells." (PMID 30053872, 2018). "N-Myc-driven neuroendocrine tumors tend to highly express NEUROD1, thereby leading to the enhanced metastatic potential." (PMID 30053872, 2018). "If drugs can be designed or screened which reduce NeuroD1 expression to levels near those seen in the normal pituitary gland, such drugs could be vital in the treatment of aggressive neuroendocrine tumors or in the prevention of their reoccurrence." (PMID 30719226, 2019). "Ideally, such a NeuroD1-targeting drug could be used for the treatment of aggressive or recurrent neuroendocrine tumor cases." (PMID 30719226, 2019). "This fact indicates that NeuroD1’s role in pathogenesis may not be limited to only pituitary tumors; it may play roles in other neuroendocrine tumors as well." (PMID 30719226, 2019). "This has now been included in this correction.The error: The author categorically stated in abstract that “N-Myc-driven neuroendocrine tumors tend to highly express NEUROD1,” but there is a controversy as to whether or not neuroendocrine lung cancer cells highly express NEUROD1." (PMID 30477547, 2018).
Cerebral ischemia (4 papers, 2016 to 2024). Restriction of arterial blood supply to the brain associated with insufficient oxygenation to support the metabolic requirements of the tissue. "The neuronal conversion of astrocytes was also observed in a rhesus monkey cerebral ischemia model through the delivery of AAV-carrying NeuroD1." (PMID 39014391, 2024). "Dr. Chen's team have also successfully established a focal cerebral ischemia model in the rhesus monkey, and successfully expressed the NeuroD1 transcription factor in the ischemic area through infection of adeno-associated virus AAV2/9-NeuroD1." (PMID 28105801, 2016).
cognitive deficit (4 papers, 2015 to 2025). "Recent studies have demonstrated that hippocampal NeuroD1 expressions were impaired in R6/2 mice and a significant reduction in hippocampal cell proliferation has been observed in R6/2 mice and another HD model mice, R6/1, suggesting the impaired neurogenesis-induced cognitive deficits." (PMID 26075247, 2015).
colorectal cancer (4 papers, 2017 to 2023). A primary or metastatic malignant neoplasm that affects the colon or rectum. "NeuroD1-silencing induces the expression of p21, a master regulator of the cell cycle, leading to G2-M phase arrest and the suppression of colorectal cancer cell proliferation and the potential of colony formation." (PMID 36977240, 2023). "In addition, NEUROD1 promotes tumor cell proliferation and tumorigenesis by directly activating the pentose phosphate pathway in colorectal cancer." (PMID 36313290, 2022). "Draxin was expressed in Tbr2 (+) late progenitors and NeuroD1 (+) neuroblasts in the dentate granule cell lineage, whereas expression of its receptor DCC (deleted in colorectal cancer) was mainly detectable in neuroblasts." (PMID 29339781, 2018).
epilepsy (4 papers, 2018 to 2025). A brain disorder characterized by episodes of abnormally increased neuronal discharge resulting in transient episodes of sensory or motor neurological dysfunction, or psychic dysfunction. "Homozygous mutations in NEUROD1 result in neurological disorders including mental deficiency, hippocampal hypoplasia, hearing loss, and epilepsy." (PMID 39264012, 2024). "It is noteworthy that two of them presented neurological disorders including epilepsy and hypopituitarism, which is supposed to be a feature of NEUROD1‐MODY." (PMID 40148250, 2025).
hepatocellular carcinoma (4 papers, 2023 to 2024). A malignant tumor that arises from hepatocytes. "Here, we found that NeuroD1 was highly expressed in hepatocellular carcinoma (HCC) cells and was associated with tumor cell death resistance." (PMID 38134213, 2023). "NeuroD1 promotes resistance to ferroptosis in hepatocellular carcinoma (HCC) by upregulating GPX4, enhancing cell survival and tumorigenic potential, highlighting it as a potential target for antitumor therapy." (PMID 39315094, 2024). "In this study, we demonstrate that NeuroD1 enhances the resistance of hepatocellular carcinoma (HCC) cells to ferroptosis." (PMID 38134213, 2023). "To investigate the role of NeuroD1 in hepatocellular carcinoma (HCC), we first analyzed its expression levels in clinical HCC samples." (PMID 38134213, 2023). "The transcription factor 4 (TCF4) and neuronal differentiation 1 (NeuroD1) can directly stimulate GPX4 transcription, thus inducing ferroptosis resistance in gastric cancer and hepatocellular carcinoma, respectively." (PMID 39624080, 2024).
schizophrenia (4 papers, 2008 to 2024). A major psychotic disorder characterized by abnormalities in the perception or expression of reality. "NEUROD1 was up-regulated in a gene expression study of the middle temporal gyrus (MTG) in schizophrenia, which may be a direct result of ATBF1 up-regulation similar to that observed in this study." (PMID 18445270, 2008). "They used this 7-miRNA signature to distinguish the schizophrenia patients from the normal controls and an AUC of 0.93 was determined using the ROC analysis, which is close to ours (0.962 for the EGR1-miR-30a-5p-NEUROD1 axis)." (PMID 28072411, 2017). "Meanwhile, some questions remain to be answered: first, it has been reported that EGR1 expression is also downregulated in the prefrontal cortex from patients with schizophrenia, we strongly felt the EGR1-miR-30a-5p-NEUROD1 axis has a role in the pathogenesis of schizophrenia." (PMID 28072411, 2017). "As the only target of miR-30e-5p, UBE21, does not have any reported role in schizophrenia, further studies were focused on schizophrenia-associated target genes of miR-30a-5p—i.e., BDNF, SMAD1, and NEUROD1, among which only NEUROD1 showed a significantly higher expression in patients." (PMID 32764320, 2020).
brain injury (3 papers, 2023 to 2025). Acute and chronic (see also brain INJURIES, CHRONIC) injuries to the brain, including the cerebral hemispheres, CEREBELLUM, and brain STEM. "For instance, following ischemic brain injury, overexpression of NeuroD1 in astrocytes enables this bHLH transcription factor to directly bind to the promoters and enhancers of neuron-related genes." (PMID 41225636, 2025). "In our study, NeuroD1 consistently converted astrocytes into GABAergic neurons both in healthy astrocytes (in vitro) and astrocytes within the peri-infarct area of hypoxic-ischemic brain injury (in vivo)." (PMID 39014391, 2024). "Recent studies have shown that in rodents or non-human primates with induced cerebral infarction, the NeuroD1-mediated transformation of astrocytes into neurons in situ can regenerate a large number of functional neurons after ischemic brain injury, thereby promoting the recovery of nerve function." (PMID 37647906, 2023).
colon cancer (3 papers, 2011 to 2023). "In the case of colon cancer, silenced TFs included well known intestinal differentiation factors such as CDX1, CDX2 and NEUROD1." (PMID 27562343, 2016).
Hyperinsulinemia (3 papers, 2014 to 2022). An increased concentration of insulin in the blood. "Interestingly, we also observed an upregulation of Neurod1 and NKx6.1, which are known to increase transcription of the insulin gene and a reduction in HNF4α transcription, known to occur during hyperinsulinemia (excess levels of insulin in the blood)." (PMID 24806840, 2014).
Impaired glucose tolerance (3 papers, 2017 to 2022). An abnormal resistance to glucose, i.e., a reduction in the ability to maintain glucose levels in the blood stream within normal limits following oral or intravenous administration of glucose. "This decreased Pdx1 and p-NeuroD1 expressions in this study was closely associated with reduced β-cell mass in the F2-HF, which led to an impaired glucose tolerance in early life." (PMID 29118817, 2017).
ischemia (3 papers, 2020 to 2022). A hypoperfusion of the BLOOD through an organ or tissue caused by a PATHOLOGIC CONSTRICTION or obstruction of its BLOOD VESSELS, or an absence of BLOOD CIRCULATION. "In the other group, ischemia was induced in only one hemisphere followed by reprogramming (FLEX-NeuroD1-mCherry), and the other hemisphere was sham-injected (ACSF) and treated with the control virus (“ET-1+NeuroD1 vs. ACSF+Control”)." (PMID 34490268, 2021). "Ngn2, but not NeuroD1, was detected in reactive astrocytes following ischemia." (PMID 36056026, 2022). "However, sovateltide treatment induced expression of DCX, HuC/HuD and NeuroD1 in the right ischemic cerebral hemispheres of rat brains at 24 h post MCAO, which suggests a role of sovateltide in maintenance and differentiation of NPCs to generate new neural cells after acute ischemia." (PMID 32728189, 2020).
lung adenocarcinoma (3 papers, 2011 to 2023). A carcinoma that arises from the lung and is characterized by the presence of malignant glandular epithelial cells. "NEUROD1 and 2 were identified by us as highly methylated in lung adenocarcinoma compared to AdjNTL." (PMID 21731750, 2011).